CD4 (CD4 molecule)
Diseases named in the same sentence as CD4 in open-access papers (continued):
Sharing a sentence is not in itself a finding about the gene and the disease.
Crohn disease (continued). "Further, a study on Crohn’s disease reported the increased frequency of CD39+CD161+CD4+ T cells in the peripheral blood and lamina propria of patients." (PMID 38714671, 2024). "Our study indicated that the proportion of HLA-DR+ CD4+ T cells in lymphocytes was positively related to the development of Crohn disease, while the proportion of naïve CD4+ T cells was negatively related." (PMID 39058862, 2024). "Flow cytometry analysis found increased peripheral CD4+ T-cells in patients with Crohn’s disease compared to controls." (PMID 38830904, 2024). "Th1 and Th17 are proinflammatory subtypes of CD4+ T lymphocytes and predominantly mediate inflammation in Crohn’s disease." (PMID 38786849, 2024). "TIM-3 dysregulation in Th1 cells was also found in patients with Crohn’s disease and correlated with imbalanced CD4 helper T cell function in ulcerative colitis." (PMID 39456777, 2024). "Peripheral CD4+ T cells were increased in patients with Crohn’s disease compared to controls (p = 0.06, Welch’s unpaired two-sample t-test)." (PMID 38830904, 2024). "Regarding a prior study, T.gondii triggers histologic alterations mediated by CD4+ T cells in a pattern similar to Crohn's disease." (PMID 37719029, 2023). "Notch/STAT-3-driven Blimp-1/c-Maf axis is a common anti-inflammatory pathway in human CD4+ T cells, which was defective in Crohn's disease patients." (PMID 37396905, 2023). "In patients with Crohn’s disease, CD4+ T cells with cytotoxic TH1 cell-like effector functions reactive against dietary and commensal yeasts are increased in blood and inflamed tissue compared with patients with ulcerative colitis and healthy controls." (PMID 37749331, 2023). "Depletion of CD4+ T by chimeric monoclonal anti-CD4 antibody is affirmative in treating patients with Crohn’s disease." (PMID 37809060, 2023). "Tissue resident CD4+ T cells are expanded in the mucosa of Crohn's disease patients and more avidly produce IL-17A and TNFα relative to controls." (PMID 37456566, 2023). "By means of exosomes, CD14+ macrophages promoted CD4+ T-cell activation-induced cell death resistance in Crohn’s disease." (PMID 37143656, 2023). "In the present study, we identified common gut commensal and food-derived yeasts, as direct activators of altered CD4+ T cell reactions in patients with Crohn’s disease (CD)." (PMID 37749331, 2023). "The addition of FANA-PGK1 or FANA-ALDOA reduced the frequency of RORC+ cells within CD4 lymphocytes obtained from patients with Crohn’s disease, this decrease trending towards significance." (PMID 36131123, 2022). "In a recent publication using mass spectrometry, HLA-DR+CD38+ CD4+ Tem were found to be enriched in lesions of Crohn’s disease patients." (PMID 36248804, 2022). "We aimed to analyze circulating CD4+ T cell subsets and cytokines during the course of Crohn’s disease (CD)." (PMID 36405740, 2022). "Our purpose was to assess the effects of different treatments on CD4+ T cells in a cohort of patients with Crohn's disease compared with healthy individuals." (PMID 35959163, 2022). "Th17 cells were differentiated from CD4 cells obtained from the peripheral blood of healthy controls and Crohn’s disease patients, upon in vitro exposure to IL-6, IL-1β, and TGF-β5,18,22." (PMID 36131123, 2022). "Several CD4+ T cell subtypes work together to maintain gut homeostasis, preventing ulcerative colitis and Crohn’s disease in a tissue laden with inflammatory antigens." (PMID 35349492, 2022). "We compared the effect of Crohn’s disease-derived ASCs from three donors on autologous CD4+ T-lymphocytes proliferation to the effect produced by a healthy subject’s precursor cells." (PMID 33924264, 2021). "Increased level of CD4+CD25+FOXP3+ T regulatory cells has been reported in Crohn’s disease and intestinal tuberculosis patients." (PMID 35153741, 2021). "In Crohn’s disease patients, vitamin D treatment also increased PD-1 expression in CD4+CD25+int T cells and reduced T cell activation." (PMID 33652978, 2021).
Crohn disease (continued). "Even more, CD4+ Foxp3+ T regs from inflamed tissue of Crohn’s disease patients were able to produce IL17 and IFNγ while retaining suppressive function." (PMID 34707610, 2021). "However CD4+ TRMs may also cause lung fibrosis and Crohn’s Disease." (PMID 34445713, 2021). "In Crohn’s disease, AhR RNA transcripts were markedly downregulated in the inflamed tissue and in the CD4 + T cells." (PMID 32764642, 2020). "On the other hand, anti-Th17 Treg cells co-expressing IL-17 and Foxp3 were shown to suppress CD4+ T cell proliferation, and found in the inflamed intestinal mucosa of patients with Crohn ́s Disease." (PMID 33542719, 2020). "Cytotoxic CD4+ T cells expressing NKG2D were identified in the lamina propria of patients with Crohn's disease." (PMID 30915067, 2019). "An increased frequency of Tfh1 and Tfh17 CD4+ T cells has been observed in peripheral blood of patients with Crohn's disease." (PMID 30915067, 2019). "Crohn’s disease in particular is characterized by a skewing of the CD4+ T cell profile toward the proinflammatory Th1 and Th17 subsets, which are believed to be critical for disease pathogenesis." (PMID 30796216, 2019). "CD4+ effector/memory T cells (Tem) were isolated from LPMCs in 15 Japanese IBD patients (ten Crohn's disease [CD] and five ulcerative colitis [UC] patients)." (PMID 29547621, 2018). "CD161, a homolog of mouse NK1.1, is expressed on CD4+ NKG2D+ T cells of patients with Crohn's disease." (PMID 28224733, 2017). "The strong positive correlation between the Oscillosipira and CD4/CD8 ratio suggests that this genus was associated with lower systemic inflammation in our cohort, which has also been shown in patients with Crohn disease and obesity." (PMID 28740260, 2017). "Some authors also describe a reduction of CD4+ T cells in the mucosa obtained from patients with Crohn’s disease when co-cultured with Lactobacillus casei and Lactobacillus bulgaricus, but no changes were observed in non-inflamed mucosa." (PMID 27820846, 2016). "NKR-P1A+ T cells can also be detected in inflammatory infiltrates in patients suffering from psoriasis and Crohn’s disease, with 20-fold more NKR-P1A+CD4+ T cells present in patients with Crohn’s disease than healthy patients." (PMID 24917862, 2014). "Further, in patients with ulcerative colitis and Crohn’s disease, the percentage of CD4+CD8α+ T cells is reduced in the intestinal mucosa, whereas the percentages in peripheral blood are increased." (PMID 23844100, 2013). "Auto-aggressive CD4 effectors, which accumulated in lymph nodes and at mucosal sites of patients with Crohn’s disease, displayed a CD47high status despite a high level of TSP-1 release in colonic tissues." (PMID 22870271, 2012). "An alternative explanation is the involvement of α4β7 in homing to the small bowel and Payer's patches in Crohn's disease compared to α4β7 involvement in colonic CD4+ T cell infiltration in the SCID adoptive transfer model." (PMID 22536543, 2012). "Abnormalities of adaptive immunity that differentiate ulcerative colitis from Crohn's disease are defined by mucosal CD4+ T cells, which were initially divided in two lineages: Th1 and Th2 T cells." (PMID 23056142, 2012). "To directly demonstrate the inflammatory functionality of intestinal Th17 cells, we sorted and activated intestinal CD4+ T cells from patients with Crohn's disease." (PMID 22176654, 2011). "Additionally, we observed increased peripheral CD4+ T cells in patients with pediatric Crohn’s disease." (PMID 38830904, 2024). "Genes in CD4+ T cells with a negative t value for association with the PRS included HAVCR1 in Crohn’s disease." (PMID 38590520, 2024). "Furthermore, in CD4+ tissue-resident memory T (TRM) cells from Crohn’s disease (CD) patients, an elevated FAO phenotype has been detected, likely due to NF-κB pathway activation." (PMID 39519064, 2024).
Crohn disease (continued). "Inhibition of FAO through Etomoxir should be explored for ERU-affected horses, as this successfully reversed the FAO-driven altered phenotype in CD4+ TRM cells in Crohn’s disease by reducing their inflammatory capacity and enhancing their apoptosis susceptibility." (PMID 39519064, 2024). "Furthermore, humoral immunity plays a vital role in the pathogenesis of Crohn’s disease in which CD4 T cells promote plasma cell differentiation in an IL-2-dependent manner." (PMID 37740772, 2024). "In addition, we observed CD8+, CD4+ and γδ T cells surrounding INFLAREs in Crohn’s disease and coeliac disease tissue, in contrast to low numbers of T cells surrounding healthy Brunner’s glands." (PMID 39567783, 2024). "The role of the immune system in Crohn’s disease biology, specifically that of pro-inflammatory CD4 T-cells, has been studied by scRNA-seq, with a recent focus on CD8 T-cells and populations of natural killer T (NKT) type II cells identified in Crohn’s disease." (PMID 37373578, 2023). "Notably, Foxp3 expressing CD4+ T cells, belong to Treg, were also able to secret IL-17 in Crohn’s disease, indicating a crossover between Th17 and Treg." (PMID 37063924, 2023). "Detection of circulating double-positive FOXP3+IL-17A+ CD4+ T cell subsets supports that T cell plasticity may reflect the inflammatory context of Crohn’s disease." (PMID 36405740, 2022). "CD4+ T cells are known as the principal drivers of Crohn’s disease." (PMID 36685554, 2022). "Although vitamin D is known to module immune responses by up-regulating the expression of PD-1 in Crohn’s disease and both PD-L1 and PD-L2 in cell-based models, vitamin D supplementation has also reduced the expression of PD-1 in CD4+ and CD8+ T cells in cystic fibrosis." (PMID 34572849, 2021). "Moreover, adoptive transfer of OVA-specific Foxp3+ CD25+ CD62Llow CD127low CD4+ T regs into refractory Crohn ́s disease patients was well tolerated and showed a clinical improvement." (PMID 34707610, 2021). "Importantly, CD47low status was maintained on CD4 effectors cells in inflamed lymphoid and mucosal tissues of patients with Crohn’s disease (CD)." (PMID 22870271, 2012). "Moreover, it has been established that CD4+ lymphocytes are predominant in the peripheral blood of patients with Crohn’s disease and the number of T alpha cells possessing IgA-specific helper activity is increased in patients with IgAN." (PMID 22866754, 2012). "We and others have previously characterized a distinct population of human CD4+ Treg cells with similarly unique type 17-like characteristics and functions, which we found enriched in the SF of patients with RA as well as in the lamina propria of patients with Crohn’s disease." (PMID 37195862, 2023). "In IBD, tissue damage occurs in areas heavily infiltrated with activated CD4+ T lymphocytes, and Th1 cell-derived cytokines are important mediators of tissue damage in Crohn’s disease, while Th2-type cytokine IL-13 may play an essential role in ulcerative colitis." (PMID 36139127, 2022). "Importantly, the mesothelial-enriched Crohn’s disease precursors activated CD4+ T-lymphocytes." (PMID 33924264, 2021). "Therefore, we next explored lean and Crohn’s disease-derived ASCs immunomodulatory properties by investigating their effect on CD4+ T-lymphocytes proliferation, as measured by CellTrace violet dye (CTV) intensity after two days of co-culture with autologous ASCs." (PMID 33924264, 2021). "An understanding of the T-bet/IFN-γ-mediated CD4+ T cell changes in the colon extends our understanding of CS-induced pathology, which may result in the development of novel therapeutic strategies to treat Crohn’s disease." (PMID 29163466, 2017). "This idea may be plausible if we were to take into account that there is a recent report showing that CD4+NKG2D+ T cells represent a key source of IL-17 in patients with Crohn’s disease and that these cells share a Th17-related phenotype, including high expression of the cytotoxicity marker CD161." (PMID 26486970, 2015).
Crohn disease (continued). "The expression of mRNA encoding inflammatory cytokines (IL2, IL17A, IL17F, IL22, IFNG, TNF, CSF2 and LTA) in CD4+ TRM cells was comparable between healthy controls and patients with Crohn’s disease." (PMID 40050432, 2025). "In the intestinal tissues of patients with IBD, CD4+ TRM cells drive the clinical relapses of IBD, including Crohn’s disease and ulcerative colitis." (PMID 39193473, 2024). "Canavan et al87 isolated T-regs (CD4 + CD25 + CD127loCD45RA- and CD4 + CD25 + CD127loCD45RA+) from a patient with Crohn’s disease and tested it in a human intestinal xeno-transplant model after being expanded in vitro." (PMID 37485563, 2023). "The absolute frequencies of B and T lymphocytes were the same between the twins except for the CD4/CD8 ratio; here, the percentage of CD19+ B cells, CD4+, and CD8+ T-cells were slightly lower in the sister with Crohn’s disease (twin 2)." (PMID 34834950, 2021). "Patients with Crohn’s disease display higher STAT1 expression, albeit only modestly in CD4+ T cells." (PMID 30796216, 2019). "Adaptive immunity to flagellin is an established feature of IBD, especially Crohn’s disease, in that IBD patients have elevations in serum antibodies (IgG and IgA) and a greater frequency of flagellin-specific CD4 T cells." (PMID 31827095, 2019). "CD4+ T cells were also increased in LPMC preparations of patients with Crohn’s disease relative to controls; however, this finding was not significant (p = 0.80, Welch’s unpaired two-sample t-test)." (PMID 38830904, 2024). "There is a unique population of TNFα + IL-17A + CD4 + T_RM cells in Crohn’s disease which are largely absent in controls." (PMID 38420127, 2024). "In addition to CD161+CD103+CD4+ TRM cells, CD127+ ILC1 cells are observed to accumulate in the damaged intestinal tissue of patients with Crohn’s disease." (PMID 39193473, 2024). "Additionally, the results of our colocalization analysis support a shared signal between the eQTL rs393727—RNASET2 in CD4 + T cells and GWAS signals for IBD (including Crohn’s disease and ulcerative colitis cases together) and more specifically only CD." (PMID 37072791, 2023). "Excessive activation of effector CD4+ T cells and/or reductions in CD4+ T cell-mediated tolerance to gut antigens are thought to play a role in the development of the two most common forms of IBD, ulcerative colitis (UC) and Crohn’s disease (CD)." (PMID 35468944, 2022). "The percentage of CD4+CD8A+ T cells among the total CD4+ T cells in the inflamed intestine of the patients with Crohn’s disease was significantly reduced compared with that in the noninflamed intestine of the patients." (PMID 36353619, 2022). "The c-Maf expressing RORγt+ Foxp3+ Treg population is also present in human colon but do not show any variation in proportion of total CD4 T cells when comparing colon from patients with Crohn's disease and healthy tissues." (PMID 32117317, 2020). "It had been demonstrated that IL-21 is produced by CD4+ but not CD8+ T cells in both Crohn’s disease and ulcerative colitis patients." (PMID 27468819, 2016). "Regarding immune dysregulation, in patients with Crohn’s disease for example, excessive amount of Th1 and Th17 cytokines, such as IFN-γ and IL-17 respectively, are secreted predominantly by the infiltrating CD4+ effecter T cells in the intestinal lamina propria." (PMID 24520376, 2014). "Consistent with elevated MHC class II, close interaction between CD4+ T cells and INFLAREs in the Crohn’s disease ileum suggests that INFLAREs may act as non-conventional professional antigen-presenting cells in chronic inflammation." (PMID 39567783, 2024). "CD4+/CD8+ and Th1/Th2 ratios were also not significantly different in patients with Crohn’s disease compared to controls in either LPMCs or PBMCs (data not shown)." (PMID 38830904, 2024).
Crohn disease (continued). "Furthermore, a unique population of CD161+CD103+CD4+ TRM cells that exert robust effector functions without TCR engagement, has been found in the intestinal tissues of patients with Crohn’s disease." (PMID 39193473, 2024). "According to a recent study, CD4+ T cell activation in the periphery may also contribute to the pathogenesis of IBD, but CD4+ T cells were found to be increased in Crohn disease but not in UC." (PMID 39058862, 2024). "We performed flow cytometry, bulk, and single-cell RNA-sequencing to profile ileal lamina propria and intraepithelial CD4 T cells (CD4CD8αα, regulatory T cells (Tregs), CD69− and CD69high Trm T cells) in controls and Crohn’s disease (CD) patients (paired non-inflamed and inflamed)." (PMID 37565620, 2023). "In humans, naïve CD8+ T cells express NKG2D, whereas CD4+ T cells generally do not express NKG2D even after activation, but its expression can be induced under certain pathological conditions, such as Crohn’s disease, juvenile-onset lupus and cytomegalovirus infection." (PMID 33995378, 2021).